AKT1 (AKT serine/threonine kinase 1)
Diseases named in the same sentence as AKT1 in open-access papers (continued):
Sharing a sentence is not in itself a finding about the gene and the disease.
melanoma (continued). "In BrafV600E-driven murine melanomas lacking Cdkn2a, AKT1 activation was shown to enhance brain metastasis, whereas AKT2 and AKT3 had a less pronounced effect." (PMID 37894325, 2023). "In summary, we provide the first evidence of a novel, isoform-specific role for AKT1 in therapy-induced senescence in human melanoma cells acting through NF-κB but independent of cGAS." (PMID 35158840, 2022). "However, IL6 expression remains dependent on AKT1 and STING, suggesting that the regulation of individual SASP factors in response to CDK4/6 inhibition in melanoma cells is complex, with compensatory mechanisms we have yet to elucidate." (PMID 35158840, 2022). "Similar to our previous results with the α2β1 integrin, this finding suggested that in signaling pathways initiated by α3β1 and α5β1, the Akt1 isoform performs a non-canonical function in regulating invasive phenotype of melanoma cells." (PMID 33260159, 2020). "Altogether, our analysis suggested that the expression profiles of nodes in motif 3 (UCA1/AKT1/hsa-miR-125b-1) can be used for quick assignment of metastatic or non-metastatic phenotypes to melanoma patients." (PMID 32703153, 2020). "Hence, we further analyzed AKT1 and AKT3 mRNA expression by qRT-PCR in both PTEN+ and PTEN− melanoma cells." (PMID 31378787, 2019). "Although some studies have demonstrated the role of p-Akt1 in several cancers, including melanoma metastases in a mice model, no studies have evaluated the prognostic value of the immunohistochemical expression of p-Akt1 in different subsets of melanomas." (PMID 30647870, 2018). "An AKT kinase domain mutant found in human melanoma (G161V) lacked enzymatic activity in vitro and in AKT1/AKT2 double knockout cells, but promoted growth factor independent survival of primary human melanocytes." (PMID 25551293, 2014). "Alterations of AKT1 and AKT2 are rare, but genetic gain of Akt3 is seen in 25% of melanoma tumors." (PMID 24743024, 2014). "We found that dafadine-A did not affect the proliferation of adherent melanoma cells, but dramatically inhibited cholesterol-induced melanoma spheroid propagation, with downregulation of Rap1A/Rap1B expression and phosphorylated AKT1-thr308/309." (PMID 38775844, 2024). "Based on the kinome reprogramming triggered by T-RECS ASO and its significant impact on AKT1 and PIM1 activities, it is possible that jointly targeting MEK and T-RECS directly inhibits both the MAPK and AKT pathways, which are the two main drivers of therapeutic resistance and melanoma progression." (PMID 38383439, 2024). "Similarly, it has been shown that the PHLPP1 phosphatase suppressed melanoma metastasis through the dephosphorylation of AKT2 or AKT3 but not AKT1 in human melanoma cells." (PMID 37894325, 2023). "The role of AKT1 in enhancing the capacity of both glycolytic and oxidative metabolism, thereby maintaining bioenergetic levels after treatments such as BRAF inhibition, makes it an important factor to study and potentially target to limit the plasticity of melanoma cells." (PMID 34831420, 2021). "In a model of a human melanoma cell line, it was demonstrated for the first time that α2β1 is involved in rescuing tumor cells from senescence; its impact was mediated by a signaling mechanism based on the non-canonic activity of Akt1 kinase." (PMID 34257160, 2021).
melanoma (continued). "Amlexanox significantly reduced the constitutive phosphorylation of p65 and p42/44 in SK-Mel-28 melanoma cells, indicating that these targets are involved in the anticancerogenous effects of IKKε/TBK1 inhibition, while Akt1 and p38 might only play a minor role in this context." (PMID 32630674, 2020). "An E17K mutation in AKT3 was also identified in one case of primary human melanoma, which may have similar functional consequences to AKT1, although this has not been functionally verified." (PMID 28082369, 2017). "Similarly, transgenic expression of constitutively active AKT1 in BRAFV600E/Cdkn2aNull non-metastatic melanoma model mice induces metastatic lesions in the brain and lung." (PMID 28082369, 2017). "In addition to using specific inhibitors of the pathways, we used shRNA approaches to simultaneously and specifically knock down Akt-1/2 and BRAF, resulting in synergistic/additive inhibition of melanoma cell proliferation, colony formation and invasion, as well as apoptosis." (PMID 19593429, 2009). "This is also consistent with our observation that tumor-derived cell lines consistently show robust phosphorylation of AKT1 when compared with other AKT isoforms, suggesting that AKT1 but not AKT2 or AKT3 plays a critical role in melanoma initiation." (PMID 37894325, 2023). "In order to investigate why AKT1 but not AKT2 impaired primary tumor growth, we analyzed cellular proliferation in our inducible AKT1 and AKT2 knockdown melanoma cell lines." (PMID 37894325, 2023). "UACC903 cells, a different human BRAF mutant melanoma cell line, showed a similar lack of beta-galactosidase staining and SASP induction in AKT1 cells, with a modest effect in AKT3 knockout cells as well, showing this phenotype is not cell-line specific." (PMID 35158840, 2022). "Recently, the comparative analysis of gene expression data of CD271+ and CD271− melanoma cells and CD271+ melanocytes identified AKT3 (but not AKT1 or AKT2) among the top up-regulated genes serving as a key mediator of survival." (PMID 32878000, 2020). "The results of this study showed that network motif UCA1/AKT1/hsa-miR-125b-1 has the highest prediction accuracy (ACC = 0.88) for discriminating metastatic and non-metastatic melanoma phenotypes." (PMID 32703153, 2020). "Gene expression analysis identified activation of AKT3, but not AKT1 or AKT2, as a major cell survival node upregulated in CD271+ melanoma-initiating cells." (PMID 31118427, 2019). "AKT3, but not AKT1 or AKT2, mediated the resistance to apoptosis in BRAF-targeted melanoma cells; promoted anchorage-independent growth in triple negative breast cancer; and controlled the VEGF-induced angiogenesis in ovarian cancer." (PMID 31470874, 2019). "Nevertheless, our finding that AKT2 knockdown greatly attenuates the metastatic potential of human melanoma cell lines is consistent with previous data, suggesting that PHLPP1 inhibits melanoma metastasis by suppressing the phosphorylation of AKT2 and AKT3 but not AKT1." (PMID 37894325, 2023).
hepatocellular carcinoma (516 papers, 2003 to 2026). A malignant tumor that arises from hepatocytes. "Dysregulation of AKT1 has been implicated in the pathogenesis of hepatoma, further highlighting its importance as a promising therapeutic target." (PMID 39502516, 2024). "AKT1 is a serine/threonine kinase, inhibition of which was found to be linked to liver injury and development of hepatocellular carcinoma in animal models, with possible implications for human clinical trials currently in progress." (PMID 30515477, 2018). "Similarly, Akt1 inhibitors hindered the proliferation of hepatocellular carcinoma cell lines and induced autophagy-associated cell death." (PMID 36499030, 2022). "The aim of this study was to see whether the AKT1 E17K mutation is common in breast, colorectal, lung, gastric and hepatocellular carcinomas and acute leukaemias." (PMID 18392055, 2008). "A comprehensive microarray study on a large number of human hepatocellular carcinoma patients shows that activation of Akt1 is one of the most consistent characteristics of HBV-induced HCC126." (PMID 39247820, 2024). "MCM7 inhibition led to a decrease in the esophagus and hepatocellular carcinomas viability, colony-forming ability, and migration capacity due to reducing phosphorylation of AKT1 and mTOR proteins with decreasing CDK1, CCNE1, and CCNE2 expression levels." (PMID 37529110, 2023). "Previous studies have shown that the differential regulation of AKT1 contributes to the development, progression, proliferation, and survival of hepatocellular carcinoma." (PMID 37511907, 2023). "ATG4B in hepatocellular carcinoma (HCC) cells is also phosphorylated by AKT Serin/Threonine Kinase 1 (AKT1)." (PMID 35456009, 2022). "In particular, the role of AKT1 in hepatocellular carcinoma and colorectal carcinoma cells is very difficult to understand." (PMID 36286049, 2022). "The results of Yang’s research implied that circRNA-ZFR and AKT1 expressions were up-regulated and miR-511 expression was down-regulated in hepatocellular carcinoma." (PMID 35186956, 2021). "miR-149 inhibits the tumorigenesis of hepatocellular carcinoma (HCC) via directly targeting AKT1 to regulate the AKT/mTOR pathway." (PMID 34869377, 2021). "For instance, miR-637 suppressed hepatoma cell viability and invasion via targetedly degrading the expression of AKT1." (PMID 34925640, 2021). "For instance, in ovarian and hepatocellular cancer AKT1 induces proliferation and tumor growth as well as migration and metastasis." (PMID 31752925, 2019). "It has been reported that miR-149-5p can inhibit cell proliferation, invasion and migration in human hepatocellular carcinoma by targeting AKT1 and further facilitating the mTOR pathway." (PMID 30717751, 2019). "Previous studies demonstrated that the overexpression of eIF3I interacted with and activated the oncogenic Akt1 by preventing the PP2A-mediated dephosphorylation of Akt-1 in human hepatocellular carcinoma." (PMID 31605257, 2019). "Other groups showed that downregulation of the AKT1/mTOR-axis using the histone deacetylase inhibitor suberoylanilide hydroxamic acid (SAHA) induced ACD in hepatocellular carcinoma (HCC) cell lines." (PMID 31671879, 2019). "In hepatocellular cancer expression of MMP9 is upregulated by AKT1 and thus controlled in the opposite direction compared to breast and colorectal cancer." (PMID 31752925, 2019). "We previously reported that PCAF upregulates cell apoptosis by inactivating Serine/Threonine Protein Kinase 1 (AKT1) signaling and consequently inhibits hepatocellular carcinoma (HCC) cell growth." (PMID 25855960, 2015). "Moreover, baicalein suppresses hepatocellular carcinoma progression through targeting the lncRNA/miR-4443/Akt1 network." (PMID 37940982, 2023). "Through the decreased expression of PI3KR1, AKT1, and BCL2 mRNA levels compared with control group, we demonstrated that the inhibition of hepatocellular carcinoma by aloe-emodin could be mediated through the PI3K-AKT signaling pathway." (PMID 37900162, 2023).
hepatocellular carcinoma (continued). "Furthermore, it was found that the Akt1 target was overexpressed in 15 out of 24 human hepatocellular carcinomas (63.3%) confirmed using PCR analysis through Northern blot." (PMID 34641448, 2021). "Co-expression of oncogenic Myc and NrasG12V, or Myc and AKT1 gave rise to multifocal liver carcinomas with HCC histology when introduced using HTVI, whereas, upon liver electroporation, the same combination of oncogenes resulted in focal iCCA or combined iCCA–HCC development." (PMID 31769429, 2019). "PI3K and AKT1 were also activated by OA in the hepatoma cell line Huh-7." (PMID 27894086, 2016). "Furthermore, inhibition of Akt1/2 and PI3K with Akt inhibitor VIII and LY294002, respectively, sensitizes hepatocellular carcinoma-derived cells for apoptotic cell death, which indicates that Akt1/2 and PI3K are prone targets for anticancer therapies." (PMID 22443451, 2012). "Both wortmannin and dominant-negative AKT1 expression vector partially reversed Taxol resistance in hepatoma cells, which further supports that AKT may coordinate the antiapoptotic activities and resulted in drug-resistant responses in hepatoma cells." (PMID 12644839, 2003). "In this study, we have found that Taxol induced AKT1 activation in Taxol-resistant hepatoma cells." (PMID 12644839, 2003). "In this study, we have found that AKT1 was activated in Taxol-treated hepatoma cells." (PMID 12644839, 2003). "Previous studies provide mechanistic evidence that AKT1 has a functional role in enhancing tumor cell proliferation and suppressing apoptosis in hepatocellular carcinoma (HCC)." (PMID 41291320, 2025). "This study provides novel insights into the mutational patterns of the AKT1 and NRAS genes in Egyptian patients with hepatocellular carcinoma (HCC)." (PMID 41291320, 2025). "The results showed that wogonin and baicalein, the main chemical components of SB, could inhibit the viability and proliferation of hepatocellular carcinoma cells, promote apoptosis through the mitochondrial apoptotic pathway, and effectively act on AKT1, RELA, and JUN targets." (PMID 36874613, 2023). "As has been reported, hsa-miR-192-5p plays a critical role in hepatocellular carcinoma by targeting multiple genes such as PIK3CA and AKT1." (PMID 41154714, 2025). "To explore the key targets and signaling pathways of Ansofaxine hydrochloride for inhibiting hepatocellular carcinoma, we first dock SRC, GRB2, PIK3R1, AKT1, and EGFR, which are in the front of the core genes." (PMID 40809022, 2025). "In hepatocellular carcinoma, the most common form of primary liver cancer, AKR1B1 has been shown to bind the kinase domain of AKT1, leading to activation of the AKT/mTOR pathway." (PMID 41154825, 2025). "We enriched the common target genes in the GO pathway and KEGG pathway and found that AKT1, RELA, and JUN are likely to be potential therapeutic targets for hepatocellular carcinoma." (PMID 36874613, 2023). "Proteins in the first group, including AKT1, PIK3CA, MAPK3, MAPK2K1, and MAPK14, have been verified to be involved in the apoptosis of hepatocellular carcinoma cells." (PMID 36817123, 2023). "Furthermore, genetic deletion of Akt1 and Akt2 in the mouse liver induces liver damage, inflammation, and paradoxically hepatocellular carcinoma (HCC)." (PMID 29687779, 2018). "Our previous study identified AKT1, AKT2 and AKT3 as unfavorable prognostic factors for patients with hepatocellular carcinoma (HCC)." (PMID 25424347, 2014). "For miR-637, many studies suggest it act as a protective factor to suppress the cancer cells proliferation, invasion and migration by targeting on regulating the expression of AKt1, RING1 or NUPRI in hepatocellular carcinoma, colorectal cancer, glioma, and cervical cancer." (PMID 32788609, 2020).
hepatocellular carcinoma (continued). "Although no mutation of Akt1 has been described to date, it is a central component of the PI3K signaling pathway that is frequently altered in hepatocellular carcinoma." (PMID 22443451, 2012). "Therefore, the effect of cyclosporin A on the reversal of Taxol resistance in hepatoma cells most likely resulted from the modulation of the PI3 kinase-AKT1 signalling pathway rather than from the regulation of the MDR transporter system of hepatoma cells." (PMID 12644839, 2003). "In accordance with previous findings, overexpression of myr-AKT1 (n=6) led to hepatic steatosis and, eventually, the development of multiple hepatocellular carcinomas (HCC) in each mouse by 28 weeks post-injection (data not shown)." (PMID 27918553, 2016). "Moreover, genome-wide analysis of gene expression in human hepatocellular carcinoma (HCC) cells demonstrates that SGK1 and its cognate kinase AKT1 are equally over-expressed when compared with normal human hepatocytes, suggesting that both kinases might have roles in hepatocellular dysregulation." (PMID 26908461, 2016).
gastric cancer (505 papers, 2005 to 2026). A primary or metastatic malignant neoplasm involving the stomach. "Obesity causally increases gastric cancer, likely mediated by persistent AKT1/IL-6/TNF upregulation." (PMID 37954072, 2023). "The major finding was a significant association of rs2494752 G variant genotypes in AKT1 with an elevated gastric cancer risk under a dominant genetic model." (PMID 26818920, 2016). "Akt1 gene amplification has been implicated in gastric carcinoma while Akt2 amplification has been linked with ovarian, pancreas, breast and stomach tumors." (PMID 24330834, 2013). "AKT1 amplification has been detected in gastric cancer and is associated with cisplatin resistance." (PMID 40041495, 2025). "Studies have found that AKT1 gene mutation could drive pathogenicity in gastric cancer, and the proliferation and apoptosis of gastric cancer cells could be regulated by affecting the expression level of AKT1." (PMID 36299773, 2022). "Similar to U373 cells, manipulation of the activity of AKT1-CREB signaling by ectopic expression of PTEN led to decreased expression of PDGFRα in HGC-27 (a Pten-deficient gastric cancer cell line) cells, and depletion of PDGFRα attenuated the proliferation of HGC-27 cells." (PMID 33568640, 2021). "The possible mechanisms of the components of the Zhishi-Baizhu herb pair in treating gastric cancer might be related to luteolin and naringenin, which intervened with the targets AKT1, MMP9, IL-6, CCND1, BCL2, MTOR, and MDM2, and are linked with the PI3K-Akt and IL-17 signaling pathways." (PMID 34899944, 2021). "In a study on gastric cancer, cancer cells increased AKT1 expression to enhance their proliferation and glycolytic capacity." (PMID 40308566, 2025). "CircNRIP1 functions as a molecular sponge, competitively binding to miR-149-5p, thereby promoting gastric cancer progression by influencing the expression level of AKT1." (PMID 40708910, 2025). "Clinical survival analysis identified four core proteins (CASP3, TNF, AKT1, and EGFR) whose abundance was associated with survival status in gastric cancer patients." (PMID 40573220, 2025). "Circ-NRIP1 acts as a sponge of miR-149-5p in gastric cancer to affect the expression level of AKT1 and ultimately as a tumor promoter in gastric cancer." (PMID 40296904, 2025). "By acting as a miR‐149‐5p sponge, circNRIP1 enhances the progression of gastric cancer (GC) via the AKT1/mTOR pathway." (PMID 39239069, 2024). "Circular RNA circNRIP1 acts as a sponge for microRNA-149-5p and promotes gastric cancer progression through the AKT1/mTOR pathway." (PMID 38459596, 2024). "For example, circRNA_0000392 promotes colorectal cancer progression through the miR-193a-5p/PIK3R3/AKT axis, and circNRIP1 acts as a miRNA-149-5p sponge to promote gastric cancer progression through the AKT1/mTOR pathway." (PMID 38658954, 2024). "Highly expressed circNRIP1 in gastric cancer can act as the sponge of microRNA-149-5p to target AKT1/mTOR pathway and improve the glucose uptake capacity of gastric cancer cells." (PMID 38177102, 2024). "TAX prevented further deterioration of gastric cancer by inhibiting the EGFR/AKT1 signaling pathway." (PMID 39086391, 2024). "The Huazhuojiedu formulas significantly inhibited AKT1, confirming their therapeutic effect in chronic atrophic gastritis and preventing gastric cancer." (PMID 39086391, 2024). "A role for AKT serine/threonine kinase 1 (AKT) and mTOR was described in tumor samples from endometrial cancer patients and in gastric cancer cells treated with metformin." (PMID 38339037, 2024). "CircNRIP1 acts as a miR-149-5p sponge to promote gastric cancer progression via the AKT1/mTOR pathway." (PMID 38459596, 2024). "Overexpressed circNRIP1 increased its adsorbing miR-149-5p; then the expression of AKT1 and mTOR which is the downstream gene of AKT1 were increased, boosting the production of lactic acid and ATP, and promoting the development of gastric cancer." (PMID 37599427, 2023).